SNORD79 (Small nucleolar RNA SNORD79 )
Gene: Small nucleolar RNA gene on chromosome 4 (184,431,966 to 184,432,049, forward strand). Ensembl gene ENSG00000251878.
Homologues: Orthologues: macaque SNORD79 (86% identical), mouse Gm50452 (69% identical), pig SNORD79 (69% identical), rat LOC120096376 (69% identical), dog SNORD79 (68% identical), tropical clawed frog SNORD79 (56% identical), zebrafish snord79.1 (56% identical), zebrafish snord79.2 (56% identical).